RNU6-428P (RNA, U6 small nuclear 428, pseudogene)
Gene: Small nuclear RNA gene on chromosome 3 (146,571,477 to 146,571,583, forward strand). Ensembl gene ENSG00000199812.
Homologues: Orthologues: macaque U6 (88% identical), pig U6 (75% identical). Paralogues in human: RNU6-16P (87% identical), RNU6-144P (86% identical), RNU6-1145P (85% identical), RNU6-1 (84% identical), RNU6-1031P (84% identical), RNU6-11P (84% identical), RNU6-15P (84% identical), RNU6-2 (84% identical), RNU6-20P (84% identical), RNU6-37P (84% identical), RNU6-393P (84% identical), RNU6-39P (84% identical), and 1286 more.